UGT2B7 (UDP glucuronosyltransferase family 2 member B7)
Description:
UDP-glucuronosyltransferase (UGT) that catalyzes phase II biotransformation reactions in which lipophilic substrates are conjugated with glucuronic acid to increase the metabolite's water solubility, thereby facilitating excretion into either the urine or bile. Essential for the elimination and detoxification of drugs, xenobiotics and endogenous compounds. Catalyzes the glucuronidation of endogenous steroid hormones such as androgens (epitestosterone, androsterone) and estrogens (estradiol, epiestradiol, estriol, catechol estrogens). Also regulates the levels of retinoic acid, a major metabolite of vitamin A involved in apoptosis, cellular growth and differentiation, and embryonic development. Contributes to bile acid (BA) detoxification by catalyzing the glucuronidation of BA substrates, which are natural detergents for dietary lipids absorption. Involved in the glucuronidation of arachidonic acid (AA) and AA-derived eicosanoids including 15-HETE, 20-HETE, PGE2, PGB1 and F2-isoprostanes (8-iso-PGF2alpha and 5-epi-5-F2t-IsoP). Involved in the glucuronidation of the phytochemical ferulic acid at the phenolic or the carboxylic acid group. Involved in the glucuronidation of the AGTR1 angiotensin receptor antagonist losartan, caderastan and zolarsatan, drugs which can inhibit the effect of angiotensin II. Also metabolizes mycophenolate, an immunosuppressive agent.
Synonyms: UDPGT 2B7; UDPGT 2B9; UGT2B9; UDPGT2B7; UDPGTH2; UDPGTh-2
Tractability: Small molecule: a high-quality ligand is known; it has a binding pocket of medium quality; it belongs to a druggable protein family. Antibody: UniProt predicts a signal peptide or a membrane-spanning region. PROTAC: its protein half-life has been measured; a small molecule that binds it is known.
Target class: Enzyme; Transferase
Safety:
Unwanted effects reported when the protein is acted on. In parentheses: how it was acted on, where the effect was seen, and who reports it.
anemia (source: ClinPGx)
opiate withdrawal symptoms (source: ClinPGx)
Gene: Protein-coding gene on chromosome 4 (69,051,363 to 69,112,987, forward strand). Ensembl gene ENSG00000171234.
Subcellular location: Endoplasmic reticulum membrane
Pathways (Reactome):
Drug ADME: Aspirin ADME; Prednisone ADME
Metabolism: Glucuronidation
Gene Ontology:
Molecular function: glucuronosyltransferase activity; retinoic acid binding; sterol 3-beta-glucosyltransferase activity; UDP-glycosyltransferase activity
Biological process: androgen metabolic process; estrogen metabolic process; xenobiotic metabolic process; lipid metabolic process
Cellular component: catalytic complex; endoplasmic reticulum membrane; membrane
Genetic constraint (gnomAD): Loss-of-function variants: 48 observed, 50.75 expected, observed/expected ratio (o/e) 0.95, 90% interval 0.75 to 1.2. The upper end of that interval is the gene's LOEUF score, 1.2, which puts it in group 5 of 6, group 1 being the genes least tolerant of losing a copy. Missense variants: 703 observed, 622.49 expected, observed/expected ratio (o/e) 1.13, 90% interval 1.06 to 1.2. Synonymous variants: 218 observed, 210.63 expected, observed/expected ratio (o/e) 1.03, 90% interval 0.93 to 1.16.
Homologues: Orthologues: chimpanzee UGT2B7 (98% identical), macaque UGT2B7 (89% identical), zebrafish ugt2a7 (53% identical), zebrafish ugt2b1 (50% identical), zebrafish ugt2b5 (50% identical), zebrafish ugt5a1 (40% identical), zebrafish si:ch73-334d15.1 (40% identical), zebrafish ugt5a2 (39% identical), zebrafish ugt5c1 (38% identical), zebrafish ugt5f1 (38% identical), zebrafish ugt5b2 (37% identical), zebrafish ugt5b4 (37% identical), and 95 more. Paralogues in human: UGT2B10 (88% identical), UGT2B11 (86% identical), UGT2B4 (85% identical), UGT2B28 (85% identical), UGT2B15 (78% identical), UGT2B17 (77% identical), UGT2A2 (61% identical), UGT2A3 (60% identical), UGT2A1 (53% identical), UGT1A1 (43% identical), UGT1A7 (43% identical), UGT1A8 (43% identical), and 9 more.
Diseases named in the same sentence as UGT2B7 in open-access papers:
UGT2B7 is named in the same sentence as 57 diseases in open-access papers, as found by Europe PMC text mining. Sharing a sentence is not in itself a finding about the gene and the disease. The quoted sentences say what the papers report.
breast carcinoma (15 papers, 2010 to 2023). "The cytochrome P450 oxidoreductase deficiency, breast cancer, bilirubin metabolic disorder, hepatocellular carcinoma, and Gilbert syndrome have the highest correlation with the abnormal expression of UGT2B7." (PMID 38068799, 2023). "Therefore, the objective of the present study was to investigate the association between certain ESR1, ESR2, HER2, UGT1A4, and UGT2B7 single nucleotide polymorphisms and breast cancer." (PMID 31888550, 2019). "Mutation in UGT2B7 was important for the growth of breast cancer, but mutations in this gene may be responsible for the development of EOC." (PMID 30970615, 2019). "Two studies investigated the role of the uridine glucuronosyltransferase 2B7 (UGT2B7)–161 SNP C to T (C > T) (rs7668258) and the incidence of cardiotoxicity in Chinese breast cancer patients." (PMID 37444400, 2023). "Their results showed that breast cancer patients with the UGT2B7 gene had a lower occurrence of cardiotoxicity." (PMID 35205681, 2022). "Even more, we observed increased levels in UGT2B7 expression when breast cancer cells were transfected with siUGDH before treating them with EPI (siUGDH + EPI)." (PMID 33572239, 2021). "Quantification of UGT mRNA in breast tissues revealed that UGT1A4, UGT1A10, and UGT2B7 mRNA levels were decreased in breast cancers as compared to normal breast tissues." (PMID 30349745, 2012). "Genes extracted from the mRNA dataset, which show great significance in the development of breast cancer, are CENPA, MACF1, UGT2B7 and SEMA3B." (PMID 35205681, 2022). "However, differ from previous studies that reported the not any statistically significant association between UGT2B7 rs12233719 SNP in all genetic models and breast cancer risk, our study found that SNP rs12233719 G>T polymorphism being a risk factor of never‐smoking female NSCLC." (PMID 33595913, 2021). "UGT2B7 and UGT1A4 showed a similar down-regulated pattern in breast cancers compared to normal breast tissues." (PMID 30349745, 2012). "This is the case for UGT2B7 induced by several anti-cancer agents in liver cell models, for UGT2B15 induced by tamoxifen and UGT2B17 induced by exemestane in breast cancer-cell models, as well as for UGT1A4 induced by fulvestrant in breast cancer and liver cell models." (PMID 32047295, 2020). "UGT1A10 and UGT2B7 were not expressed in 1 normal breast specimen and 12 and 25 breast cancers, respectively." (PMID 30349745, 2012).
epilepsy (8 papers, 2010 to 2022). A brain disorder characterized by episodes of abnormally increased neuronal discharge resulting in transient episodes of sensory or motor neurological dysfunction, or psychic dysfunction. "Epilepsy patients with the promotor UGT2B7 rs28365063 −161C > T genetic variant showed an increased clearance of the antiepileptic drug lamotrigine due to higher gene expression of the UGT2B7 enzyme." (PMID 34198586, 2021). "Allelic and genotype frequencies of the metabolism enzymes UGT1A4 and UGT2B7 in Chinese patients with epilepsy." (PMID 31404235, 2019). "Therefore, it is recommended that the patients of epilepsy with mutant UGT2B7 C802T gene be given a relatively high dose of VPA for the initial treatment." (PMID 35290166, 2022). "In addition, more studies have revealed significant effects of the UGT2B7 C161T (rs7668258) and UGT2B7 T125C (rs7668282) polymorphisms on the VPA C0/D ratio in Chinese children or adults with epilepsy." (PMID 33553069, 2020). "Used in clinical treatment of epilepsy, the dose of OXC can be individualized based on the UGT2B7 genotype." (PMID 35290166, 2022). "In our study, we found the relationship between the SNPs screened from SCN1A, SCN2A and UGT2B7, respectively, and VPA responses in Chinese Han people with epilepsy." (PMID 32185219, 2020). "A meta-analysis showed that UGT2B7 variants G211T and C161T, but not T802C, affect the pharmacokinetics (PK) of VPA in patients with epilepsy." (PMID 33553069, 2020).
hepatocellular carcinoma (5 papers, 2016 to 2023). A malignant tumor that arises from hepatocytes. "CD4, UGT2B7, and CYP3A4 were selected as the potential diagnostic biomarkers of non-alcoholic fatty liver disease–hepatocellular carcinoma." (PMID 37089050, 2023). "We found that the expression level of CHRNA4 and nicotine metabolism genes, including CYP2A6, FMO3, UGT2B7 were dramatically down-regulated in human hepatocellular carcinoma, suggesting disrupted nicotine metabolism in hepatocellular carcinoma." (PMID 28583088, 2017). "Zidovudine at the concentration from 2 to 100 μM can activate UGT2B7 in human liver carcinoma cell line (HepG2), in contrast, it showed a downtrend from 50 to 2500 μM in human thyroid carcinoma cell (THLE2)." (PMID 27847477, 2016).
diabetes (3 papers, 2023 to 2025). "In the human liver and kidney, diabetes significantly lowers UGT2B7 enzymatic activity, mRNA expression, and protein levels." (PMID 36670981, 2023). "Studies have revealed the evidence that mRNA expression of UGT2B7 was down-regulated in diabetes." (PMID 36670981, 2023). "Moreover, diabetes mellitus also reduces the enzymatic activity and expression of phase II metabolizing enzyme UGT2B7." (PMID 36670981, 2023). "The activity and mRNA expression of UGT2B7 were not significantly modulated in rats treated with n-hexane, chloroform, and ethyl-acetate extracts of F.cretica after diabetes induction, implying that these extracts had no potential to modulate drug pharmacokinetics." (PMID 36670981, 2023).
liver cancer (3 papers, 2017 to 2024). An epithelial or non-epithelial malignant neoplasm that arises from the liver. "The TPM of UGT2B7, a non‐coding RNAs marker of liver cancer, was 0.098 in plasma and 6.18 in urine." (PMID 35858042, 2022). "UDP-glucuronosyltransferase 2B7 (UGT2B7) has been identified as a subtype classification biomarker for hepatocellular adenoma and one as a gene signature that can accurately predict microvascular invasion in HCC, indicating its importance in liver cancer." (PMID 39548390, 2024).
melanoma (3 papers, 2012 to 2022). A malignant, usually aggressive tumor composed of atypical, neoplastic melanocytes. "The effect of complete loss of UGT2B7 activity (or all UGT activity) would be predicted to have an even greater impact on the sensitization of melanoma to these anthracyclines." (PMID 23110092, 2012). "To test the role of glucuronidation in melanoma drug resistance directly, UGT2B7 was knocked down in WM115 cells, the only melanoma cell line we have identified with UGT expression thus far." (PMID 23110092, 2012). "We utilized RNA interference and glucuronidation assays to examine the role of UGT2B7 on melanoma cell survival." (PMID 23110092, 2012). "Consistent with the UGT expression pattern observed in melanocytes, the primary melanoma cell line WM115 exhibited only UGT2B7, UGT2B10 and UGT2B15 expression." (PMID 23110092, 2012). "This hypothesis is strengthened by demonstration that knockdown of UGT2B7 in melanoma cells sensitized these cells to anti-cancer agents known to be metabolized by glucuronidation." (PMID 23110092, 2012). "Treatment of WM3211 or metastatic melanoma cell lines with anti-cancer agents (including vemurafenib) induced expression of UGT2B7, UGT2B10 and UGT2B15 demonstrating that melanoma cells retain the ability to re-express these same three UGTs." (PMID 23110092, 2012). "Only a few reports have been published, including research on UGT expression in melanocytes derived from newborn foreskin tissues, with UGT2B isoforms (UGT2B7, UGT2B10, and UGT2B15) being expressed primarily in normal melanocytes as well as in a primary melanoma cell line." (PMID 35682955, 2022). "UGT2B7 expression was demonstrated in human melanocytes, but not cell lines derived from metastatic melanomas." (PMID 32382038, 2020). "Interestingly we demonstrate that UGT2B7, UGT2B10 and UGT2B15 can be re-expressed in melanoma cells in response to the anti-cancer agents." (PMID 23110092, 2012).
pancreatic cancer (3 papers, 2017 to 2023). "The co-expressed genes of the NT5DC family, including UGT2B7, MT1G, ACADL, MT1H, and others, were found to be associated with pancreatic cancer in previous studies 37-40." (PMID 37576396, 2023). "A modulation of lipid storage levels by overexpression of the UGT2B7 enzyme was also recently uncovered in breast and pancreatic cancer cell line models." (PMID 28217095, 2017). "The interplay between UGT enzymes and lipid homeostasis is also supported by the perturbed accumulation of lipid droplets induced by the expression of UGT1A9 and UGT2B7 in HEK293, breast and pancreas cancer cell models." (PMID 36295907, 2022).
prostate carcinoma (3 papers, 2021). A carcinoma that arises from epithelial cells of the prostate gland. "Many studies have revealed associations between genetic variation in UGT2B7 and cancer risk, including breast and prostate cancer." (PMID 33595913, 2021).
AIDS (2 papers, 2015 to 2016). A syndrome resulting from the acquired deficiency of cellular immunity caused by the human immunodeficiency virus (HIV). "Genetic variation in CYP2A6, NR1I3 (coding for constitutive androstane receptor-CAR), and UGT2B7 has also been shown to be associated with significantly elevated efavirenz concentrations among HIV/AIDS patients." (PMID 26402689, 2015).
anemia (2 papers, 2021 to 2025). A reduction in the number of red blood cells, the amount of hemoglobin, and/or the volume of packed red blood cells. "A UGT2B7 variant called UGT2B7 -900A>G (rs7438135) was associated with a higher risk of leukopenia and anemia." (PMID 40630120, 2025).
breast tumor (2 papers, 2012 to 2025). "UGT2B7 activation disrupts the estrogen homeostasis in breasts, exacerbating breast tumor metastasis." (PMID 40927361, 2025). "In the present study, we characterized the mRNA expression of UGT1A1, UGT1A4, UGT1A8, UGT1A10, and UGT2B7 in normal and breast tumor tissues from AA and EA women." (PMID 30349745, 2012).
colon cancer (2 papers, 2015 to 2025). "Consistent with the UGTs expression profile, M2 was detected in HT29 cell S9 fractions while M1 was undetectable, which can be explained with the absence of UGT2B7 in the colon cancer cells." (PMID 25692465, 2015).
colorectal cancer (2 papers, 2017 to 2022). A primary or metastatic malignant neoplasm that affects the colon or rectum. "As both increased LCA level and altered gut microbiota are risk factors for colorectal cancer, this can be a potential reason of higher UGT2B7 expression in the livers from metastatic patients compared to deceased organ donors." (PMID 34741761, 2022).
liver dysfunction (2 papers, 2021 to 2023). "Among the studied UGTs, the most abundant isoenzyme was UGT2B7, and the least one was UGT1A3, irrespectively of the stage of liver dysfunction." (PMID 34575411, 2021).
alcoholic liver diseases (1 paper, 2021). A disorder caused by damage to the liver parenchyma due to alcohol consumption. "Alcoholic liver disease and primary biliary cholangitis were involved in the most prominent changes in the protein abundances, with downregulation of 6 (CYP1A2, CYP2C8, CYP2D6, CYP2E1, CYP3A4, UGT2B7) and 5 (CYP1A1, CYP2B6, CYP2C8, CYP2E1, CYP3A4) significantly downregulated enzymes, respectively." (PMID 34575411, 2021).
bladder cancer (1 paper, 2017). "Their data showed that a UGT2B7 polymorphism (T/T genotype) was much more prevalent in the Chinese population than for Caucasians, and this SNP was found in a higher prevalence of bladder cancer cases compared with healthy controls (25 vs. 9% OR)." (PMID 27690298, 2017).
cholestasis (1 paper, 2015). Impairment of the bile flow caused by obstruction within the liver, or outside the liver in the bile duct system. "In particular for diclofenac-induced cholestasis, it was suggested that allelic variants in UGT2B7, CYP2C8, and MRP2 may cause an increase in the level of reactive metabolites leading to protein-diclofenac adducts that then produce toxicity." (PMID 26582990, 2015).
Cirrhosis (1 paper, 2025). A chronic disorder of the liver in which liver tissue becomes scarred and is partially replaced by regenerative nodules and fibrotic tissue resulting in loss of liver function. "Since UGT enzymes contribute to the metabolism of asciminib, for severe HI, a ‘modified Sim-Cirrhosis CP-C’ population, accounting for the reduced activity of UGT2B7 and UGT1A4 in such patients, was also used." (PMID 41155903, 2025).
endometrial cancer (1 paper, 2025). Primary or metastatic malignant neoplasm involving the endometrium (mucous membrane that lines the endometrial cavity). "Genetic alterations of the SHBG gene are also correlated with a lower risk of ovarian cancer, endometrial cancer, or esophageal squamous cell carcinoma, whereas some alleles increase the risk of non-small lung cancer—UGT2B7." (PMID 40427034, 2025).
esophageal cancer (1 paper, 2022). A primary or metastatic malignant neoplasm involving the esophagus. "UGT1A1 and UGT2B7 expression that were recently reported in esophageal cancer tissues." (PMID 36295907, 2022).
hepatocellular adenoma (1 paper, 2024). A benign epithelial neoplasm arising from the hepatocytes. "Moreover, our research found consistent downregulation of UGT2B7 in hepatocellular adenoma." (PMID 39548390, 2024).
lung adenocarcinoma (1 paper, 2021). A carcinoma that arises from the lung and is characterized by the presence of malignant glandular epithelial cells. "Comparing to low UGT2B7 expression, patients with high UGT2B7 expression had significant poor overall survival among never‐smoking female Asian lung adenocarcinoma patients with EGFR mutation (HR = 4.80, 95% CI = 1.18–14.21, p = 0.027)." (PMID 33595913, 2021).
neutropenia (1 paper, 2017). A decrease in the number of neutrophils found in the blood. "With regard to NLE (the secondary study aim), the study reported that rs4148350 and rs246221 in ABCC1 and rs76688282 in UGT2B7 were significantly associated with prolonged grade 3–4 or deep neutropenia." (PMID 29100455, 2017).
prostate tumours (1 paper, 2020). "Similar to normal prostate tissue, prostate tumours expressed several UGT2B mRNAs, including UGT2B17 but also UGT2B4, UGT2B7, UGT2B10, UGT2B11, UGT2B15 and UGT2B28." (PMID 32047296, 2020).
renal cell carcinoma (1 paper, 2023). "One rRE, a GAAA-repeat expansion, located near a regulatory element in the first intron of UGT2B7 was detected in 34% of renal cell carcinoma samples and was validated by long-read DNA sequencing." (PMID 36517591, 2023).
sickle-cell anemia (1 paper, 2021). "However, sickle-cell anemia patients with the promotor variant UGT2B7 rs7668282 TT genotype required a lower morphine dose because they had a higher capacity of morphine glucuronidation compared to patients with the UGT2B7 rs7668282 CC genotype." (PMID 34198586, 2021).
skin rashes (1 paper, 2021). "In this context, inhibition of UGT2B7 is well-documented to elevate lamotrigine levels when co-administered with VPA by 2–3 folds increasing the risk for dose-dependent life threatening skin rashes associated with lamotrigine." (PMID 34468892, 2021).
Stroke (1 paper, 2024). Sudden impairment of blood flow to a part of the brain due to occlusion or rupture of an artery to the brain. "Elderly stroke patients with severe hepatic and renal impairment may experience reductions in hepatic and renal blood flow rates, albumin levels, hematocrit values, as well as protein abundance levels of UGT2B7." (PMID 39771574, 2024).